ALB (albumin)
Diseases named in the same sentence as ALB in open-access papers (continued):
Sharing a sentence is not in itself a finding about the gene and the disease.
Ascites (continued). "After conservative treatment of diuretics, albumin administration, and repeated drainage for ascites, decreased urine volume, increased serum creatinine, and persistent ascites occurred." (PMID 35978331, 2022). "The occurrence of PHG was significantly associated with gender, haemoglobin, platelet count, prothrombin time, albumin, Child–Pugh stage, EV, GV and ascites (P < 0.05)." (PMID 36241992, 2022). "A previous study revealed that liver dysfunction, including low levels of serum albumin and platelet count, is a prognostic factor for the prevalence of ascites." (PMID 35351001, 2022). "The occurrence of PHG was related to gender, haemoglobin, platelet count, prothrombin time, albumin, Child–Pugh stage, EV, GV and ascites." (PMID 36241992, 2022). "Terlipressin and albumin are treatments for refractory ascites, but both require intravenous access and are expensive." (PMID 36060403, 2022). "Within 3 months after commencing treatment, we detected a significant deterioration in factors representing liver functional reserve including the Child–Pugh score, albumin-bilirubin (ALBI) score, serum albumin level, and the presence of ascites (p < 0.001)." (PMID 36551574, 2022). "We have compared multiple outcomes regarding the use of midodrine in cirrhotic ascites to albumin and standard medical treatment." (PMID 36060403, 2022). "Point changes from baseline in the levels of albumin, bilirubin, and ascites were the most common contributors to the development of the Child–Pugh B status at Week 8 for patients in both the cabozantinib and placebo arms." (PMID 35397508, 2022). "One of the criticisms of our study was the low recovery rate of total protein and albumin in the processing of ascites (44.9 and 49.0%, respectively)." (PMID 35287609, 2022). "Intergroup differences in the preoperative recipient factors (i.e., MELD score, the incidence of ascites, DM, hemoglobin level, albumin level, platelet count, INR, and D-dimer level) were detected." (PMID 35054144, 2022). "The CP grade has five parameters, the bilirubin, albumin, prothrombin time, hepatic encephalopathy, and ascites." (PMID 35845571, 2022). "Serum-ascites albumin gradient (SAAG) is an initial and useful measure to differentiate causes of ascites." (PMID 35178310, 2022). "During the waiting period, many of the children suffered from a deterioration in their condition: 31/55 (56.4%) experienced worsening ascites and 32/55 (58.2%) required albumin infusions during the waiting period." (PMID 35456234, 2022). "Low SAAG ascites has been reported in up to 20% of those with malignant ascites in prior reports and in our cohort, the serum albumin levels were low in our cohort (median 1.99, IQR 1.83–2.13)." (PMID 36064324, 2022). "Mean albumin was 4.1 g/dL (SD 0.5) and the only two patients who presented values below 3.5 g/dL (3.2 and 2.2 g/dL) also had ascites." (PMID 36514502, 2022). "The scoring of ascites in CP classification was considered to be subjective and interrelated with serum albumin levels." (PMID 35566676, 2022). "The reasons for that are as follows: the grading of ascites was believed to be highly subjective; the distinction between mild and moderate ascites was subject to interobserver variability; and the ascites and serum albumin level were interrelated." (PMID 35845571, 2022). "Regarding adverse events (AEs), the development of ascites was observed significantly more frequently in modified albumin–bilirubin (mALBI) 2b/3 patients than in mALBI 1/2a patients (54.5% vs. 25.0%, p = 0.03)." (PMID 35740647, 2022). "Post-TIPS ascites was improved (P < 0.001), and albumin levels (34.7 g/L [33.1–36.8]) had an increasing trend (P = 0.134) compared with pre-TIPS levels (33.2 g/L [30.2–36.8])." (PMID 35183265, 2022). "For non-BA parameters, creatinine, INR, protime AST, bilirubin, AST/ALT, and MELD increased the odds of having ascites, whereas albumin and ALT decreased the odds of having ascites." (PMID 35402050, 2022).
Ascites (continued). "The Serum Albumin Ascites Gradient (SAAG) was >1.1 g/dl in all of the patients with ascites with a mean value of 2.12±0.62." (PMID 35633208, 2022). "Liver function was graded using Child–Pugh score (CPS), which is comprised of five factors: total bilirubin, serum albumin, prothrombin time, and presence of ascites of hepatic encephalopathy." (PMID 35628976, 2022). "With the elevation of ALB level, the colloid osmotic pressure increased, the degree of liver cirrhosis and portal pressure decreased, and the amount of ascites was gradually reduced." (PMID 35035357, 2021). "Albumin infusions have been standard after the therapy of hepatogenic ascites by large-volume paracentesis for over 25 years." (PMID 34836265, 2021). "A total of 13 titrated albumin-solutions as well as 48 samples (29 ascites/pleural effusions from patients with malignancy; 19 from patients without malignancy) were examined." (PMID 33782528, 2021). "The only exception, so far, is represented by the recently released Italian clinical practice guidelines, that include albumin among the medical treatment options for decompensated patients with ascites." (PMID 34830508, 2021). "CTP score included grade of encephalopathy, ascites, PT, total bilirubin, and albumin which is more suitable to the ACLF defined by APASL." (PMID 33820919, 2021). "Higher drain amount in cirrhotic patients can be attributed to postoperative ascites and lower levels of albumin." (PMID 33513179, 2021). "Among these, the Child-Pugh score has been extensively validated and comprises degree of ascites, prothrombin time, serum levels of bilirubin and albumin, and severity of hepatic encephalopathy." (PMID 34976412, 2021). "The Child–Pugh score, based on clinical symptoms of insufficient liver function (ascites/encephalopathy), and laboratory analysis of parameters of liver function (albumin, bilirubin, and PT) can be used to identify low or high-risk patients." (PMID 34823485, 2021). "In question 6A we asked physicians which amount of 20% albumin solution they would administer after a paracentesis of 5 l of ascites (i.e., LVP)." (PMID 33270161, 2021). "The patient was then administered an IV albumin to correct the reduced albumin level and abdominal ascites." (PMID 34797336, 2021). "There were significant differences in gender, CTP class, etiology, the presence of ascites, BMI, the presence of sarcopenia, visceral adiposity, albumin, creatinine, and PT-INR." (PMID 34901116, 2021). "It was clearly demonstrated that repeated daily infusions of 20 g albumin for 30 days were necessary to reach the elimination of ascites and reduction of the need for diuretic therapy." (PMID 34281177, 2021). "Low albumin was demonstrated to be a common complication in cirrhotic patients that can lead to ascites or edema and account for their increased mortality." (PMID 34055994, 2021). "Currently, treatment with intravenous albumin is indicated for the prevention of circulatory dysfunction after large-volume paracentesis for ascites removal (using plasma expansion to counter hypovolemia), the prevention and management of the HRS, and in SBP." (PMID 34836265, 2021). "A remarkable finding was that patients frequently received peripheral supplemental infusion of albumin solution due to continuous deterioration of nutritional status and ascites." (PMID 34022800, 2021). "CP classification includes serum albumin, bilirubin, and prothrombin time but also includes the presence of hepatic encephalopathy and ascites, so the results obtained by CP classification contain a certain degree of subjectivity." (PMID 34840628, 2021). "The presence of ascites, high Eastern Cooperative Oncology Group (ECOG) status, low albumin, and extent of surgery were associated with higher 30-day mortality on univariate analysis." (PMID 35096617, 2021). "Of the 15 patients with ascites, 2 had reduced albumin levels (23 g/L; both had protein-losing enteropathy)." (PMID 33033916, 2021).
Ascites (continued). "The parameters (e.g., ascites, hepatic encephalopathy, albumin, total bilirubin, creatinine, ammonia, and prothrombin time) that strongly correlated with other parameters were considered confounding factors and excluded from statistical analysis." (PMID 33892649, 2021). "After standard anti-tuberculosis therapy, her systemic symptoms completely resolved while ascites worsened with serum-ascites albumin gradient >11 g/L." (PMID 34778328, 2021). "The PRECIOSA study (NCT03451292; 1.5 g/kg body weight per week after hospital discharge in patients with uncomplicated ascites) will provide further insights into the efficacy of different pre-emptive albumin administration regimens." (PMID 34131658, 2021). "Large amounts of diuretics including furosemide, spironolactone, and human atrial natriuretic peptide and albumin administration together with intensive evaluation of intravascular volume are required to control massive ascites." (PMID 32993506, 2020). "Currently, Child-Pugh scoring consists of ascites, hepatic encephalopathy (HE), prothrombin time, serum albumin level, and total bilirubin level." (PMID 33214947, 2020). "A mean baseline MELD score of 10.1 was reported for the CP B group (n = 21), and 95% of these patients (20/21) had clinical features of decompensation (ascites, 81% [17/21]; hepatic encephalopathy, 67% [14/21]; median albumin, 3.2 g/dL)." (PMID 32270053, 2020). "It primarily comprised of ascites, hepatic encephalopathy (HE), nutritional status, total bilirubin, and albumin." (PMID 33214947, 2020). "Child–Pugh score system is the most common methods of evaluating the liver function, which is classified by total bilirubin (TB), albumin (ALB), prothrombin time (PT), ascites and psychosis (hepatic encephalopathy HE)." (PMID 33183305, 2020). "Although compensated chronic liver disease is a requirement for loco-regional therapy, the appearance of early ascites seems to be related to the history of prior ascites, lower haemoglobin levels and lower albumin." (PMID 32487071, 2020). "The meaning of infusion of albumin during dialysis in this context is similar to the infusion of albumin in the case of ascites drainage in cirrhotic hypoalbuminemic patients." (PMID 32188148, 2020). "Second, albumin levels and grade of ascites are inadequate to put together for one grading system, since they are interrelated variables." (PMID 33392064, 2020). "The evaluation indicators included serum total bilirubin, albumin level, hepatic encephalopathy, ascites, and prothrombin time (PT)." (PMID 33336028, 2020). "The decrease of ALB is common in liver cirrhosis with ascites and other liver functions (such as acute hepatic necrosis, toxic hepatitis, etc.)." (PMID 32503634, 2020). "History of ascites decompensation, haemoglobin and albumin were independently related to the development of early ascites." (PMID 32487071, 2020). "Midodrine is as effective as albumin in reducing morbidity and mortality among patients with refractory ascites undergoing LVP at a significantly lower cost." (PMID 32704299, 2020). "The Child-Pugh score is calculated according to serum levels of bilirubin and ALB, prothrombin time, degree of ascites, and severity of hepatic encephalopathy." (PMID 33415154, 2020). "On the other hand, CTP includes biosynthetic parameters such as circulating albumin, bilirubin, and coagulation characteristics, and subjective parameters such as the presence and severity of ascites and encephalopathy." (PMID 33364092, 2020). "The decreased serum level of albumin and the formation of ascites considerably contributed to the deterioration to CP-B." (PMID 33050527, 2020). "Concerning long-term outcomes, variables such as serum albumin or bilirubin levels, ascites, encephalopathy, and prothrombin time for the Child-Pugh score are the most common independent predictors of mortality in patients with liver cirrhosis." (PMID 31948392, 2020).
Ascites (continued). "Some of the variables included in this system were interrelated (e.g., ascites and serum albumin levels)." (PMID 32913457, 2020). "A Japanese prospective study found improvement of serum albumin in cirrhotic patients with serum albumin at 3.5 g/dL or less and the presence of ascites, peripheral edema, or hepatic encephalopathy." (PMID 32429077, 2020). "They found that five baseline factors of body mass index, encephalopathy, ascites, and serum levels of alanine aminotransferase and albumin were related to a reduction of the Child–Pugh score to class A." (PMID 32442193, 2020). "The assessed factors of Child-Pugh grading were TB level, serum ALB, PT or international normalized ratio, degree of ascites and degree of hepatic encephalopathy." (PMID 31710641, 2019). "In conclusion, this retrospective controlled study comparing CART and simple paracentesis in ascites patients is the first to demonstrate that concentrated ascites reinfusion can significantly elevate serum albumin level." (PMID 31308465, 2019). "That is, it includes several subjective items (ascites and encephalopathy) and interrelated items (ascites and serum albumin)." (PMID 31540447, 2019). "We selected a homogenous population of patients who had large-volume ascites, which we defined as those who were hospitalized and underwent paracentesis with a fluid volume and blood albumin concentration of >3 L and <3.0 mg/dL, respectively." (PMID 31035484, 2019). "CTP classification semi-quantitative assessment included five common clinical and laboratory indicators and they are ascites, degree of hepatic encephalopathy, coagulation, serum albumin, bilirubin levels." (PMID 30917853, 2019). "Patients with ascites had lower sodium, higher creatinine, lower white blood count, higher platelet count, higher albumin, and lower total bilirubin." (PMID 31120995, 2019). "At the same time, reduced synthesis of albumin, increased portal vein pressure, and ascites were observed due to hypohepatia." (PMID 31781658, 2019). "Second, some of the indexes in the C-P class, such as ascites and serum albumin, are closely interconnected." (PMID 31191834, 2019). "The Dengue Score is a model for predicting pleural effusion and/or ascites and uses the hematocrit (Hct), albumin concentration, platelet count and aspartate aminotransferase (AST) ratio as independent variables." (PMID 29471786, 2018). "The correct timing of the surgical operation is elective surgery after ascites drainage and albumin/electrolyte serum level and coagulation alteration correction." (PMID 30065783, 2018). "The Child-Pugh (CP) classification incorporates five parameters: serum albumin, bilirubin, coagulation profile, ascites and encephalopathy." (PMID 29988960, 2018). "Scientific reports indicate that adequate preparation of cirrhotic patients, with control of ascites, albumin and electrolytes serum levels, nutritional support, and coagulation patterns, allows for the success of elective surgery." (PMID 30065783, 2018). "This was done by removing the ascites and encephalopathy components, leaving a system with a combined point score based on albumin, bilirubin and PT ratio added to the serum arterial lactate concentration." (PMID 28374334, 2017). "The amounts of both total protein and albumin were significantly higher in the exudative ascites than in the transudative ascites (P< 0.001)." (PMID 28510606, 2017). "After CART, the calculated amounts of total protein and albumin in transudative ascites were 49.2 ± 31.1 g and 25.8 ± 18.0 g, while those in exudative ascites were 83.9 ± 43.0 g and 47.7 ± 26.0 g, respectively." (PMID 28510606, 2017). "Univariate analysis showed that age, TBIL, Na, INR, ALB, Cr, ascites, infection, HE, UGIB, LAAR and MELD score differed significantly between survivors and those who died within three months." (PMID 29312647, 2017).
Ascites (continued). "The Child-Pugh score is based on clinical symptoms (ascites and encephalopathy), bilirubin and albumin levels, and prothrombin time." (PMID 29108327, 2017). "In a meta-analysis of BCAA supplementation therapy, increases in albumin levels and reductions in ascites and edema were reported." (PMID 29108327, 2017). "One patient suffered transient liver dysfunction with pleural effusion and ascites that resolved with albumin therapy and diuresis." (PMID 28830467, 2017). "The five variables are bilirubin, albumin, prothrombin time, ascites, and presence of hepatic encephalopathy." (PMID 28951631, 2017). "The Child-Pugh score comprises fiver parameters: ascites, hepatic encephalopathy, bilirubin, albumin, and prothrombin time." (PMID 28951631, 2017). "It has been shown that cirrhotic patients with ascites benefit from albumin therapy by preventing postparacentesis circulatory dysfunction." (PMID 28800610, 2017). "Other signs of leakage were right sided pleural effusion and ascites which were confirmed radiologically and low albumin levels (2.4 g/dl)." (PMID 27165581, 2016). "In this quasi experimental interventional study patients of liver cirrhosis and ascites with HRS type I were treated with intravenous albumin and incremental dosage of terlipressin based on response with maximum dose of 12mg/day." (PMID 27182222, 2016). "Compared with hematocrit and albumin level, pleural effusions and/or ascites as visualized by ultrasonography (USG) are highly sensitive and specific for determining plasma leakage." (PMID 27391122, 2016). "For practicality, we selected the lowest albumin concentration at the critical phase as the predictor of pleural effusion and/or ascites because it is only measured once." (PMID 27391122, 2016). "Male gender, ascites and low albumin were the only statistically significant predictors of hospital readmission, p<0.05." (PMID 27780274, 2016). "Fluid leakage phase was evidenced by development of pleural effusion and ascites and was supported biochemically with >20 % rise in hematocrit and low serum albumin (2.4 g/dL)." (PMID 27165581, 2016). "Some studies showed that the recurrence of ascites decreased for patients with good diuretic response when combined with albumin." (PMID 27103467, 2016). "Serum CA-125 levels significantly correlated with ascites volume, serum level of alanine aminotransferase, aspartate aminotransferase, albumin, and Rotterdam BCS scores." (PMID 26451141, 2015). "When the presence of ascites was considered, the plasma levels of AOPPs-albumin were higher, as well as TNF-α." (PMID 26665009, 2015). "In the context of preeclampsia, ascites is usually due to hypoproteinemia and a low albumin/globulin gradient resulting in a low intravascular oncotic pressure." (PMID 26171264, 2015). "The limitations to the scoring system include subjectivity in ascites and encephalopathy grading, variable PT results, and a “ceiling” and “floor” effect for arbitrary cut-off points with bilirubin and albumin, respectively." (PMID 26203357, 2015). "Some were according to the assessment of a combination of laboratory parameters (serum bilirubin, serum albumin, prothrombin time international normalized ratio) and clinical parameters (encephalopathy and ascites)." (PMID 25265536, 2014). "Currently, albumin level, encephalopathy, and ascites can be altered by medical intervention, including administration of branched-chain amino acids, Zn preparations, and diuretics." (PMID 24322305, 2014). "The Child-Pugh (CP) score, which is calculated according to the serum albumin and bilirubin levels, the prothrombin time (PT), and the presence and degree of encephalopathy or ascites, is a system for assessing hepatic function." (PMID 24779518, 2014).